MUC4 (mucin 4, cell surface associated)
Diseases named in the same sentence as MUC4 in open-access papers (continued):
Sharing a sentence is not in itself a finding about the gene and the disease.
colon carcinoma (16 papers, 2006 to 2025). "Based on this funding, we aimed to further identify whether MUC4 mutation is the independent prognostic factor for colon cancer using Cox regression analysis." (PMID 33714943, 2021). "Furthermore, MUC4 mutations have been implicated in the poor prognosis of colon cancer." (PMID 39338204, 2024). "Thus, we speculated that MUC4 mutation with a high TMB in colon cancer might drive the immune system to fight against tumor cells." (PMID 33714943, 2021). "This study aimed to investigate the effect of 8 weeks of quercetin supplementation combined with intermittent exercise on the protein levels of intestinal Muc5Ac, Muc4, and polyphosphate in rats with chemically induced colon cancer." (PMID 40969596, 2025). "Recently, an antibody to Mucin 4 (MUC4) conjugated to a fluorescent probe has shown promise in targeting colon tumors in orthotopic mouse models." (PMID 39458160, 2024). "In the case of colon cancer, the loss of MUC2 and MUC4 and the gain of MUC4, MUC5AC, and MUC16 are associated with oncogenic progression." (PMID 39767713, 2024). "Our analysis showed a significant (p<0.05) down-regulation of MUC4 expression in CRC patients compared to normal individuals by using The Cancer Genome Atlas (TCGA-COAD) database (containing 286 colon cancer and 41 normal samples)." (PMID 35255004, 2022). "We were unable to show a relationship between DNA methylation status and expression of the MUC4 gene in the LS174T colon cancer cell line, similarly to our results for MUC1." (PMID 19127263, 2009). "In this study, we show that the DNA methylation pattern is intimately correlated with MUC4 expression in breast, lung, pancreas and colon cancer cell lines." (PMID 19127263, 2009). "Further, the ability of SMC/Muc4 to alter ErbB2 localization in polarized human colon carcinoma CACO-2 cells has been demonstrated, indicating a strong physical association between the two molecules." (PMID 16551361, 2006). "Similarly, in the case of colon cancer, loss of MUC2 and MUC4 and gain of MUC5AC and MUC16 expression have been reported temporally with oncogenic progression." (PMID 36980526, 2023). "Therefore, our results demonstrated that the changed tumor-infiltrating immune cells induced by MUC4 contribute to the antitumor immunity of colon cancer." (PMID 33714943, 2021). "Thus, we speculated that MUC4 mutation might positively regulate CD4 and CD8 T cell while negatively regulate Tregs in colon cancer." (PMID 33714943, 2021). "In conclusion, MUC4 may have important clinical implications for immune therapy of colon cancer." (PMID 33714943, 2021). "Therefore, it is necessary to investigate the relationship between MUC4 and colibactin, and focusing on MUC4 might reveal a new strategy to prevent colon cancer." (PMID 27829225, 2017). "When evaluating new biomarkers for colon cancer, MUC1, MUC2, MUC4, MUC5AC, and MUC6 are currently documented in the largest bodies of work regarding their role in the progression from normal colonic tissue to malignancy." (PMID 36900282, 2023). "MUC4 rs2688513 AG genotype was significantly less frequent in the colon cancer group, although its significance was not maintained in the FDR-P test." (PMID 37384668, 2023). "Other mucins, such as MUC2, MUC4, and MUC5AC, can also be considered for designing a mucin-based panel for serum profiling or histopathological analysis of tissue biopsies for the screening of colon cancer." (PMID 36980526, 2023). "Altogether, this suggests that MUC4/MUC16/MUC20high signature would be useful in stratification of patients with worst prognosis in several carcinoma and notably pancreatic, stomach and colon cancers." (PMID 30236127, 2018).
pancreatic adenocarcinoma (16 papers, 2004 to 2023). "The MUC4 gene (Mucin c, which is linked to pancreatic adenocarcinoma) is the principal constituent of mucus." (PMID 37372431, 2023). "In this study, we aimed at identifying and characterizing miRNAs activated downstream of MUC4-associated signaling in pancreatic adenocarcinoma." (PMID 34944818, 2021). "We aimed at characterizing microRNAs activated downstream of MUC4-associated signaling in pancreatic adenocarcinoma." (PMID 34944818, 2021). "MUC4 is also a tumor-associated antigen, whose overexpression is observed in various epithelial malignancies, such as pancreatic adenocarcinoma and breast, lung, ovarian, and prostate cancer." (PMID 27829225, 2017). "Consistent with previous reports (Jonckheereet al., 2004)MUC4 expression was detected in the pancreatic adenocarcinoma cell lines CAPAN-1 and CAPAN-2." (PMID 34796278, 2021). "This transcriptional up-regulation leads to increased expression of MUC4 in pancreatic adenocarcinoma." (PMID 27829225, 2017). "Transmembrane mucins, MUC4 and MUC16 are associated with tumor progression and metastatic potential in human pancreatic adenocarcinoma." (PMID 24204560, 2013). "In contrast, most studies using 1G8, which was raised against rat ASGP-2, described that MUC4/1G8 expression is related to a favorable outcome, although one study of pancreatic adenocarcinoma described that MUC4/1G8 expression is related to poor survival." (PMID 23152882, 2012). "Our earlier studies have shown the specific and differential expression of MUC4 in pancreatic adenocarcinoma as compared with the normal pancreas or chronic pancreatitis." (PMID 19738614, 2009). "We have previously studied the generation of immune responses after vaccination with tumor-associated carbohydrate antigen (TACA)-containing glycopeptides from the tandem repeat (TR) sequence of MUC4, an aberrantly expressed mucin in pancreatic adenocarcinomas." (PMID 30952968, 2019). "This indicated increased energy generating ability of MUC4-expressing cells that might enhance the tumorigenicity and metastatic potential of pancreatic adenocarcinoma cells." (PMID 17595659, 2007). "However, our understanding about the role of MUC4 in the development and progression of pancreatic adenocarcinoma is still unclear." (PMID 17595659, 2007). "A TGFβ2-dependent increase in MUC4 expression in pancreatic adenocarcinoma and elevated levels of TGFβ2 transcripts in MUC4-expressing OT tumours suggest the involvement of this cytokine in MUC4 regulation by autocrine and/or paracrine manner in CD18/HPAF tumours." (PMID 14760381, 2004). "In pancreatic adenocarcinoma, TFAP2A interacts with the mucin 4 (MUC4) promoter to suppress MUC4 expression, which prevents cell proliferation and invasion." (PMID 37291585, 2023).
lymph node metastasis (14 papers, 2009 to 2024). "Univariate analysis showed that MUC4 expression (p = 0.047), differentiation (p < 0.05), T-stage (p < 0.05) and lymph node metastasis (p < 0.001) were significantly associated with poor survival." (PMID 23101681, 2012). "The backward stepwise multivariate analysis showed that MUC4 expression (p = 0.039) and lymph node metastasis (p = 0.001) were significant independent risk factors." (PMID 23101681, 2012). "MUC4 was activated during the process of cervical squamous dysplastic transformation, aberrantly expressed in cervical cancer, and associated with lymph node metastasis." (PMID 33664766, 2021). "On the other hand, the MUC4/1G8 expression was related with lymphatic invasion (r = 0.395, P = 0.001) and lymph node metastasis (r = 0.296, P = 0.045)." (PMID 23152882, 2012). "Backward stepwise multivariate analysis showed that MUC4 expression (P = 0.039) and lymph node metastasis (P = 0.001) were statistically significant independent prognostic factors." (PMID 23101681, 2012). "The MUC4/1G8 expression was related with lymphatic invasion (r = 0.395, P = 0.001) and lymph node metastasis (r = 0.296, P = 0.045)." (PMID 23152882, 2012). "In the paired samples, 37.2% of lymph node metastases expressed higher MUC4 levels than patient-matched primary tumors, while only 9.3% expressed lower levels." (PMID 19761616, 2009). "tested samples of MPLC with lymph node metastasis (LNM) and found that the genes with the highest mutation frequencies in this pair were MUC16, FLNA, MUC4, FAT3, SETD2, and CALR, which implied that MPLC with LNM may have a unique mutation spectrum." (PMID 39411141, 2024). "The high-confidence driver genes RHPN2, MUC16, and MUC4 were significantly mutated in both small- and large-sized rNEN specimens, whereas mutations in MAN2A1, and BAG2 were only identified in large-sized specimens diagnosed with lymph node metastases." (PMID 39548061, 2024). "The MUC4/1G8 expression was related with lymphatic invasion and lymph node metastasis." (PMID 23152882, 2012). "To assess MUC4 expression in breast tissue, we examined nine commercially obtained TMAs encompassing over 600 samples of individual and patient-matched normal tissue, primary tumor and lymph node metastases." (PMID 19761616, 2009). "Immunohistochemistry of prognostic factors showed that there were significant differences in MUC4 expression under different conditions such as ages, depth of invasion, TNM stage, lymph node metastasis, and distant metastasis (Table." (PMID 31915505, 2019). "Relationship between expression of MUC4 and MUC1 and lymphatic invasion (ly), venous invasion (v) or lymph node metastasis (N)." (PMID 23152882, 2012). "Additionally, chi-squared tests demonstrated significant correlations between the expression of MUC4 and age, depth of invasion, TNM stage, lymph node metastasis, and distant metastasis." (PMID 31915505, 2019). "This multivariate analysis showed that none of MUC4 expression (P = 0.079), lymph node metastasis (P = 0.080), T stage (P = 0.511), and differentiation (P = 0.291) were significant risk factors affecting the outcome." (PMID 23101681, 2012). "None of the expression of MUC1, MUC2, and MUC4 was significantly related to gender, age, differentiation, lymph node metastasis, or depth of invasion." (PMID 23101681, 2012). "To further assess whether the MUC1 and/or MUC4 methylation status affect prognosis, we divided patients into two groups based on the presence or absence of lymph node metastasis." (PMID 27283771, 2016). "For lymph node metastasis, higher MUC1 expression was related to poor prognosis (n = 11, RR = 1.40, 95% CI: 1.14-1.72, p = 0.002), but MUC4 was not (n = 2, RR = 1.23, 95% CI: 0.82-1.83, p = 0.317)." (PMID 29221212, 2017). "For mucins with equal expression in SBC lesions and normal tissue, MUC4 expression was not related to any prognostic factors, but MUC6 was related to lymph node metastasis." (PMID 24722639, 2014).
cervical cancer (11 papers, 2017 to 2024). A primary or metastatic malignant neoplasm involving the cervix. "The differences in MUC4 expression patterns between dysplastic and normal endocervical epithelia may be useful as a diagnostic marker for predicting cervical cancer." (PMID 27829225, 2017). "Abrogation of MUC4 expression reduces invasion and the mesenchymal properties of cervical cancer cells." (PMID 33664766, 2021). "Recently, some researchers found that miR211 inhibited invasion and epithelial-to-mesenchymal transition of cervical cancer cells via targeting MUC4." (PMID 31333725, 2019). "MiR-211 has been reported as a potential suppressor of MUC4 and shown to inhibit cervical cancer cell invasion and epithelial-to-mesenchymal transition (EMT)." (PMID 29739335, 2018). "MUC4 is overexpressed in cervical cancer tissues, with the highest level of MUC4 expression in high-grade dysplasia." (PMID 27829225, 2017). "MUC4, which is a transmembrane glycoprotein expressed higher in cervical dysplasia than in benign cervical epithelium, is also related to lymph node metastasis of cervical cancer." (PMID 33557879, 2021). "In addition, we found significantly recurrent mutations in TTN (33%), MUC4 (31%), and MUC16 (19%), here reported for the first time, to our knowledge, in cervical carcinomas." (PMID 33664766, 2021). "Therefore, the recurrent site-specific TTN and MUC4 mutations and the known role of these genes in cancer suggest the possibility that mutant TTN and MUC4 may exert oncogenic activity in cervical cancer." (PMID 33664766, 2021). "In cervical cancer, MUC1, MUC4 and MUC20 were reported to be overexpressed in the squamous type." (PMID 38702644, 2024).
endometriosis (11 papers, 2011 to 2025). The growth of functional endometrial tissue in anatomic sites outside the uterine body. "In 2020, the polymorphism rs2291651 inthe MUC4 gene was described to be an accompanying sign of endometriosis inSouth Korean women." (PMID 37153512, 2023). "Screening identifiedeight genetic variants of MUC4, including rs2291651, whose presence correlatedwith the development of endometriosis." (PMID 37153512, 2023). "Both MUC2 and MUC-4 have been shown to be crucial to successful implantation, polymorphisms of each being linked to endometriosis and infertility." (PMID 33193109, 2020). "Genetic alterations of mucin genes, such as MUC2 and MUC4, were previously identified to be associated with endometriosis and related infertility." (PMID 26285705, 2015). "In humans, polymorphisms in the MUC4 nucleotide sequence have been significantly associated with the development of endometriosis and endometriosis related infertility." (PMID 22039891, 2011). "With endometriosis as a possible cause of infertility in women, we also would like to study the association of MUC4 single-nucleotide polymorphisms (SNPs) with susceptibility to endometriosis-related infertility." (PMID 21349170, 2011). "Our data prove the association of MUC4 polymorphisms with advanced stages of endometriosis and the related infertility." (PMID 21349170, 2011). "To correlate MUC4 polymorphism with the risk of endometriosis and endometriosis-related infertility, we performed a case-control study of 140 patients and 150 healthy women." (PMID 21349170, 2011). "In this study, we observed an association of MUC4 polymorphism with endometriosis development and endometriosis-related infertility in a Taiwanese population." (PMID 21349170, 2011). "MUC4 polymorphisms are associated with endometriosis development and endometriosis-related infertility in the Taiwanese population." (PMID 21349170, 2011). "Significantly, the frequency of haplotype T-T was found to be higher in patients than in controls (P = 0.0353), suggesting the association of MUC4 SNPs with endometriosis development." (PMID 21349170, 2011). "In this study, Pro4135Ser (rs2688513) and Ala4693Ser (2246901) substitutions in the putative functional domains of MUC4 were found to be associated with advanced stages of endometriosis." (PMID 21349170, 2011). "A Mucin 4 (MUC4) gene indel mutation was detected at the same site in four patients, which could be associated with endometriosis-related infertility." (PMID 40486679, 2025). "Interestingly, genetic polymorphisms in MUC2 and MUC4 were recently reported to be associated with endometriosis development and the related infertility." (PMID 26285705, 2015). "Because these endometriosis-associated SNPs can cause amino acid substitutions, the biofunctions of MUC4 might be altered by changes in hydrophilicity and protein folding." (PMID 21349170, 2011). "The purpose of this study was to evaluate whether genetic variations in MUC4 associate with endometriosis in the Taiwanese population." (PMID 21349170, 2011). "However, MUC4 polymorphisms are associated with the risk of endometriosis in Korean women." (PMID 38313170, 2023). "In addition, MUC4 is associated with advanced stages of endometriosis." (PMID 35741699, 2022). "Since endometriosis has been suspected as one potent factor leading to infertility in women, we also studied the possible linkage between MUC4 SNPs and infertility." (PMID 21349170, 2011). "More detailed studies are needed to investigate the biochemical pathways regulated by MUC4 during the development of endometriosis." (PMID 21349170, 2011). "Because of the functions involved in the acquisition of adhesion ligands or receptors and the loss of antiadhesion, proteins such as MUC4 and MUC1, the two major mucins present in endometrial epithelium, thus become suspect in endometriosis development." (PMID 21349170, 2011).
endometriosis (continued). "Our findings support the functional roles of MUC4 SNPs in regulating cellular mobility and invasion of endometrial cells during endometriosis development and progression." (PMID 21349170, 2011). "However, the true mechanism of how MUC4 modulates the pathogenesis of endometriosis and infertility was not clearly understood." (PMID 21349170, 2011). "Mucin 4 (MUC4) plays an important role in protecting and lubricating the epithelial surface of reproductive tracts, but its role in the pathogenesis of endometriosis is largely unknown." (PMID 21349170, 2011). "Because this is a hospital-based study with a modest sample size, enrollment of a larger cohort based on a population approach could help to elucidate the functional role of MUC4 in endometriosis and the related infertility." (PMID 21349170, 2011). "Since the extracellular domain of MUC4 is critical for HER2 interaction and cell invasiveness, these defined SNPs located in putative functional domains of MUC4 may play important roles during endometriosis development and progression." (PMID 21349170, 2011).
dry eye (9 papers, 2011 to 2024). "Further analysis of the circadian disruption-induced dry eye model suggested that MUC4 deficiency was essential for pathogenesis." (PMID 38956298, 2024). "In summary, chronic jet lag induces dry eye by reducing the level of the transmembrane mucin MUC4 in the cornea." (PMID 38956298, 2024). "To investigate the effect of supplemental MUC4 on jet lag-induced dry eye, we performed lissamine green staining and corneal fluorescein staining." (PMID 38956298, 2024). "In the in vivo CEC mice dry eye experiment, mice treated with the fraction of < 10 kD and < 3 kD had higher tear secretion level, stronger expression of ZO-1 and MUC4, higher goblet cell density, and better-preserved microvilli." (PMID 34750552, 2021). "In our present study, we observed thinning of the corneal epithelium of dry eye mice in the immunohistochemical staining for Muc4." (PMID 27886047, 2016). "Given the significant decrease in MUC4 in the cornea in the chronic jet lag model, we explored whether MUC4 is a critical molecule in jet lag-induced dry eye." (PMID 38956298, 2024). "This suggests the intriguing hypothesis that Muc4 is required to maintain mucosal epithelial differentiation, over and above any role in inflammatory diseases such as dry eye." (PMID 37604830, 2023). "Therefore, we can only demonstrate that MUC4 partially regulates chronic jet lag-induced dry eye." (PMID 38956298, 2024). "The evolution of the dry eye condition was assessed by histology, immunohistochemistry staining, scanning electron microscopy, and gene expression by using TaqMan gene assay technology (mucin-4 [MUC4], matrix metallopeptidase-9 [MMP9], tumor necrosis factor-α [TNF-α], and defensin β-2 [DEFB2)." (PMID 21245952, 2011). "Overexpression of MMP9, MUC4, and HBD2 was observed at 24 h following the treatment with 100 μL sodium hyaluronate 0.15% (SH) of dry eye condition in comparison with the control corneal tissue (p < 0.001; Student’s t-test)." (PMID 34959420, 2021). "Furthermore, melatonin, a circadian rhythm restorer, had a therapeutic effect on jet lag-induced dry eye by restoring the expression of BMAL1, which upregulated MUC4." (PMID 38956298, 2024). "Thus, in the absence of symptomatic dry eye postvitreo-retinal surgery, conjunctival changes in the form of reduced goblet cell density, altered MUC4, MUC16, AQP5 and cytokines are suggestive of dry eye at a molecular level and based on goblet cell density." (PMID 32437405, 2020).